NRG1 (neuregulin 1)
Diseases named in the same sentence as NRG1 in open-access papers (continued):
Sharing a sentence is not in itself a finding about the gene and the disease.
Cognitive impairment (continued). "Furthermore, a number of studies have suggested that NRG1 administration can ameliorate cognitive impairments in cerebral ischemia and neurodegenerative diseases." (PMID 29875654, 2018). "Accordingly, the observed cognitive deficits that resulted from the haploinsufficiency of Nrg1 and the reduction of GABAergic transmission in our male TMc-Nrg1 mutant mice were likely to be ameliorated by the upregulation of the GABAergic system due to chronic valproate injections." (PMID 24782733, 2014). "Thus, it is possible that elevated inactive lever pressing may reflect cognitive impairment in Nrg1 mutants." (PMID 37233814, 2023). "Interestingly, either haploinsufficiency of Nrg1 or overexpression of Nrg1 in mice can result in some types of cognitive deficits, which implies a possible U-shaped relationship between Nrg1 expression and cognitive function, which has been reported for the COMT gene." (PMID 24782733, 2014). "Given the diverse actions of NRG1 from alternatively spliced isoforms, it is not surprising that forms of NRG1 have also been reported to provide modest beneficial effects after the onset of cognitive impairments in AD mouse models." (PMID 37903620, 2023). "We selected the age of 13 months (later phase and not the early phase of cognitive deficits) to allow a more obvious measurement of the effects of NRG1." (PMID 26913607, 2016). "Interestingly, protracted treatment with valproate ameliorated observed cognitive deficits and the reduction of hippocampal GAD67 expression in our male TMc-Nrg1 mutant mice." (PMID 24782733, 2014). "Additionally, several pathways including the ERBB4 signaling pathway (adjusted p = 2.82 × 10-3), driven by ERBB4, NRG1, and NRG3 may contribute to cognitive impairments." (PMID 42193047, 2026). "BACE1 levels are increased in AD brains and cerebrospinal fluid (CSF) and may lead to enhanced NRG1 secretion, but no study has assessed CSF NRG1 levels in AD and mild cognitive impairment (MCI) patients." (PMID 32690068, 2020).
psychosis (27 papers, 2007 to 2025). "Here, we investigated granule cell (GC) subtype composition in the dentate gyrus (DG) and the influence of a psychosis-associated V321L mutation in Neuregulin1 (Nrg1)." (PMID 40280713, 2025). "We assessed GC heterogeneity in a mouse model harboring a missense mutation in the Nrg1 gene, which was previously associated with psychosis." (PMID 40280713, 2025). "We previously characterized a psychosis-associated missense mutation in the NRG1 gene showing that it resulted in reduced stem cell proliferation, increased neuronal differentiation, and altered dendritic branching of GCs in the DG." (PMID 40280713, 2025). "The V321L mutation in Nrg1 was discovered using a family-based association test where it was found to be overtransmitted to offspring with psychosis and SCZ." (PMID 39214704, 2024). "To date, several genes have been associated with the pathophysiology of psychosis, including neuregulin 1(NRG1), brain-derived neurotrophic factor (BDNF), and catechol-O-methyltransferase (COMT), along with the others." (PMID 31447712, 2019). "Nevertheless, variants of the BDNF and the NRG1 have been associated with dimensions of psychosis across diagnostic boundaries." (PMID 31447712, 2019). "The NRG1 gene has been associated replicably with risk for psychotic illness and with structural and functional neuroimaging abnormalities in psychosis." (PMID 29201594, 2017). "We examined associations of DAO, DAOA, and NRG1 SNPs with risk profiles in individuals at risk for psychosis." (PMID 29326614, 2017). "The white matter integrity of the ATR has been widely reported to be decreased in psychiatric disorders and in psychosis-risk-associated neuregulin-1 variants." (PMID 24146131, 2015). "A single nucleotide polymorphism in NRG1 has also been associated as a risk factor to positive symptoms of psychosis in a proportion of late-onset AD." (PMID 20405009, 2010). "Additionally, both Type III Nrg1 heterozygous mice and mice deficient in γ-secretase show sensorimotor gating deficits, an endophenotype of psychotic disorders." (PMID 39214704, 2024). "Thus, there is ambiguity regarding the association of DAOA and NRG1 polymorphisms with the transition to psychosis." (PMID 29326614, 2017). "Further studies examining the frequency of the exon 11 T allele in control individuals from the CVCR, and LD in the vicinity of the exon 11 variant should help determine whether the NRG1 allele actually does contribute to psychosis in this population." (PMID 17519028, 2007). "About 46% of the NRG1 rs4281084 AA genotype UHR carriers (n = 13) and 44% of the T-allele UHR carriers (n = 45) transitioned to psychosis within a 15-year follow-up period." (PMID 29326614, 2017). "In a 3-year prospective study cohort of 185 individuals (age: 13–35 years) at high risk and ultra-high risk (UHR) for psychosis, we assessed DAO (rs3918347, rs4623951), DAOA (rs778293, rs3916971, rs746187), and NRG1 (rs10503929) SNPs and their mRNA expression." (PMID 29326614, 2017). "We observed an association between Neuregulin 1 (NRG1) and auditory hallucinations in patients with psychosis (p = 5.25 × 10−6, Z = 4.40), as well as between the gene encoding pericentriolar material 1 (PCM1) and auditory hallucinations (p = 4.47 × 10−4, Z = 3.32)." (PMID 40943654, 2025). "An interesting result of our research was that patients with the combined genotypes of AA for COMT rs4680 and AA for NRG1 rs3924999 may have a later onset of psychosis than those with either AG/AG or AG/GG of COMT rs4680/NRG1 rs3924999." (PMID 39062492, 2024). "An interaction ANOVA revealed that NRG1 rs3924999 significantly impacted cognitive flexibility scores, with chronic patients showing significantly lower scores compared to those experiencing their first episode of psychosis (p-adj = 0.03)." (PMID 39518545, 2024).
psychosis (continued). "This study highlighted the complex interplay of genetic factors in treatment response and suggested that combined COMT and NRG1 genotypes might influence the onset of psychosis." (PMID 39062492, 2024). "A missense mutation in Nrg1 resulting in a single amino acid substitution in a transmembrane valine (to leucine; rs74942016—results in Val→Leu at Position 321 in Type III Nrg1 β1a) was found to be associated with SCZ (and more strongly with psychosis) in a Costa Rican population." (PMID 39214704, 2024). "Furthermore, recent evidence also suggested that NRG1 is an appropriate candidate gene for Meth-induced psychosis and overexpression of NRG1 type III modulated the behavioral tests induced by Meth." (PMID 34484386, 2021). "Thus, members of the NRG1 gene family have been modified in mutant mice to result in a variety of psychosis-related phenotypes." (PMID 29201594, 2017). "We here report the impact of the Neuregulin-1 rs35753505 variant on white matter structure in healthy young individuals with no family history of psychosis." (PMID 24683514, 2014). "Seven psychosis-implicated SNPs across five different genes (proxies of ZNF804A-rs1344706, CACNA1C-rs1006737, BDNF-rs6265, DISC1-rs2793092, DISC1-rs11122319, NRG1-rs6994992 and NRG1-rs35753505 itself) were examined in our independent sample for effects on brain volume." (PMID 36168994, 2022). "Moreover, in the opposite direction, for assessing high-mood state across all subjects, NRG1 has a modest AUC of 58% (p = 1.4E−02), but is a robust predictor of all future hospitalizations for mania in patients with psychotic disorders (OR of 2.7 (p = 3.3E−02)." (PMID 33828235, 2021). "Association analyses of age-at-onset, number of mood episodes, and presence of psychosis, substance abuse and/or suicidal ideation suggested modest contributions of genes such as RTN4, XKR4, NRXN1, NRG1/3 and GRK5 to disease characteristics." (PMID 38570518, 2024). "Genome-wide linkage studies of autism have not highlighted chromosome 8p12, where NRG1 is located, and autism is not characterized by psychosis." (PMID 17519028, 2007). "In short, the role of NRG1 rs221533 in psychosis as well as in neurodevelopment is still not fully understood, and its expression may be influenced by other genetic, epigenetic, or environmental factors." (PMID 24278715, 2012). "Our results are in contrast to a study, which showed that NRG1 (type I and II isoforms) mRNA expression was significantly lower in blood of UHR individuals who transitioned to psychosis (n = 31) compared to non-converters (n = 66) and controls (n = 50)." (PMID 29326614, 2017).
lung adenocarcinoma (26 papers, 2015 to 2026). A carcinoma that arises from the lung and is characterized by the presence of malignant glandular epithelial cells. "WNT10A, PDGFA, TNF, and NRG1 had been identified as important paracrine factors from infiltrated dendritic cells to regulate neuropathic pain associated with lung adenocarcinoma." (PMID 32434423, 2020). "The chimeric CD74-NRG1 (Cluster of Differentiation 74-Neuregulin-1) gene derived by the chromosome 8 rearrangement is recently reported as the first potentially treatable oncogenic driver alteration associated with this specific pattern of lung adenocarcinoma." (PMID 29515761, 2018). "NRG1 fusions were also identified as novel oncogenic driver mutations in lung adenocarcinoma." (PMID 26486077, 2015). "Pancreatic ductal carcinomas and lung adenocarcinomas are aggressive and deadly cancers, among which rare tumors harbor NRG1 fusions making the NRG1-rearranged tumor candidates suitable for specific targeted therapies." (PMID 40723230, 2025). "As such, Odintsov and his colleagues established two cell line models from NRG1-rearranged (Neuregulin-1) lung adenocarcinoma samples and showed via transcriptome analysis the activation of the mTOR pathway in these NRG1 fusion-bearing samples." (PMID 39796653, 2024). "There were 6 genes with a causal relationship to lung adenocarcinoma, including FUBP1, CTD-2012J19.3, CTD-2012J19.1, DCBLD1, NRG1 and SECISBP2L." (PMID 38834983, 2024). "Partial responses were achieved for up to 12 months in lung adenocarcinoma and 10 months in invasive mucinous adenocarcinoma of the lung harboring NRG1 fusion." (PMID 38399524, 2024). "In the present study, we have found that conditional overexpression of ERK3 in lungs cooperates with PTEN deletion to promote the formation of lung adenocarcinoma at least partially owing to upregulation of NRG1/ERBB3 signaling." (PMID 34719109, 2022). "In summary, our study shows that conditional ERK3 overexpression cooperates with PTEN deletion to promote the formation of lung adenocarcinoma at least partially by upregulating NRG1/ERBB3 signaling." (PMID 34719109, 2022). "TNF, WNT10A, PDGFA, and NRG1 derived from infiltrated dendritic cells in lung adenocarcinoma microenvironment were proved to worsen neuropathic pain associated with cancers by sensitizing sensory neurons." (PMID 32434423, 2020). "NRG1 fusion genes in lung adenocarcinoma have been reported for the first time in 4 of 15 (27%) Asiatic IMAs." (PMID 29515761, 2018). "NRG1 fusions are found in a novel molecular subset of lung adenocarcinomas with distinct mucinous features." (PMID 27626312, 2016). "The frequency of NRG1 fusions was reported to be approximately 1.7% in lung adenocarcinomas from an Asian population." (PMID 26486077, 2015). "NRG1 suppresses human lung adenocarcinoma through AKT and ERK1/2 pathway." (PMID 33568633, 2021). "In addition, recurrent NRG1 gene fusions have been reported in lung adenocarcinoma; NRG1-altered models may prove useful to further test the applicability of NRG1 as a therapeutic target." (PMID 30036377, 2018). "First, NRG1 gene fusion is more commonly observed in lung adenocarcinoma, with invasive mucinous adenocarcinoma (IMA) and acinar adenocarcinoma being the most prevalent pathological subtypes in cases with NRG1 fusions." (PMID 38957319, 2024). "In a previous study of 115 surgically resected lung adenocarcinoma patients, tumor coexpression of HGF and neuregulin 1 (NRG1; a cell adhesion molecule) occurred more frequently in tumors > 3 cm in size." (PMID 29398577, 2018). "Some pancreatic ductal-type (PDADK) and lung adenocarcinomas (LADK) lacking other molecular drivers are reported to harbor NRG1 fusions as potential novel therapeutic targets." (PMID 40723230, 2025). "CD74-NRG1 fusions, originally found in non-smoking lung adenocarcinoma patients, provide the ligand for ERBB2-ERBB3 receptor complexes through the extracellular expression of the EGF-like domain of NRG1 III-β3." (PMID 35804895, 2022).
lung adenocarcinoma (continued). "By screening 102 lung adenocarcinomas negative for known oncogenic alterations, they found that NRG1 was present in 4 out of 15 of the invasive mucinous adenocarcinoma (IMA) subtype." (PMID 34680187, 2021). "Furthermore, gene amplifications of avian erythroblastic leukemia viral oncogene homolog 2 (ERBB2), MET, ROS1, Neuregulin 1 (NRG1), neurotrophic tyrosine kinase receptor 1 (NTRK1), and RET have also been found in lung adenocarcinoma." (PMID 28105432, 2016). "In addition, multiple gene fusions, such as NRG1, RET, and ALK, were only detected in IMA patients in our cohort and the detecting rate (16/51, 31.4%) of gene fusions was significantly higher than the unselected lung adenocarcinoma patients." (PMID 33505917, 2020).
Alzheimer disease (25 papers, 2006 to 2025). A progressive, neurodegenerative disease characterized by loss of function and death of nerve cells in several areas of the brain leading to loss of cognitive function such as memory and language. "The association of miR-143-3p with NRG1 was initially explored in Alzheimer’s disease models, where the inhibition of miR-143-3p promoted neuronal survival by targeting NRG1, thus indicating a protective role against cell apoptosis." (PMID 40149647, 2025). "Plasma soluble NRG-1 has been detected as a diagnostic biomarker for Alzheimer’s disease." (PMID 29636063, 2018). "Accumulating evidence supports a protective role of NRG1 signaling in neuroinflammation, particularly in Alzheimer’s disease (AD) models." (PMID 41150741, 2025). "Neuregulin, particularly neuregulin-1 (NRG1), is essential for oligodendrocyte development and the regulation of myelination, processes that are notably disrupted in Alzheimer's disease." (PMID 39285941, 2024). "We have previously reported the neuroprotective effects of NRG1 in cell models and in a transgenic mouse model of Alzheimer’s disease." (PMID 30328584, 2019). "Recently, we reported that NRG1 attenuates cognitive function impairments in a transgenic mouse model of Alzheimer’s disease." (PMID 30328584, 2019). "NRG1 protects neurons under various conditions of stress, including ischemia, organophosphate-induced neural injury, and Alzheimer’s disease." (PMID 30328584, 2019). "Due to the fact that it also cleaves amyloid precursor protein, BACE1 is a therapeutic target in Alzheimer’s disease, however, consistent with its role in NRG1 processing we find that BACE1 inhibition significantly impairs myelination in our co-culture system." (PMID 28334857, 2017). "Selective, targeted disruption of neuregulin-1 signaling on brain microglia with GlyB4 could be a novel “upstream” approach to slow or stop disease progression in Alzheimer’s disease." (PMID 37903620, 2023). "Selective disruption of NRG1 signaling in microglia using GlyB4 could be a novel approach to block disease progression in patients with Alzheimer’s disease." (PMID 37903620, 2023). "In summary, this study we have also identified important genes (NRG1, NEDD9, IRF5, IFI35, STAT1, STAT2, JAK2, IL3RA), and alterations in biological processes and pathways that may be associated with Alzheimer’s Disease." (PMID 34484988, 2021). "In Alzheimer’s disease (AD) brains, NRG1 accumulates in neuritic plaques." (PMID 32690068, 2020). "NRG1/ErbB-dependent modulation of synaptic plasticity in the hippocampus has been reported also in pathological contexts, as in animal models of neurological and psychiatric disorders, like Angelman’s syndrome (AS) and Alzheimer’s disease (AD)." (PMID 31906113, 2019). "Highlights of the conference included reports on brain imaging, the discovery of mutations in the progranulin gene that cause frontotemporal dementia, the finding that neuregulin-1 is a substrate for BACE1 and new interest in the connection between Alzheimer's disease and metabolic syndromes." (PMID 16956414, 2006). "Similarly, plasma NRG1 levels (which correlate with cerebrospinal fluid levels) were found to be higher in patients with Alzheimer’s dementia as compared to neurologic controls (p < 0.001), further implicating the role of NRG1 in the pathogenesis of neurodegenerative diseases." (PMID 38369520, 2024). "Regarding the nervous system, the presence or absence of the NRG1 gene has shown a relationship with Alzheimer’s disease." (PMID 34680187, 2021). "Several lines of evidence suggest that neuregulin 1 (NRG1) signaling may influence cognitive function and neuropathology in Alzheimer’s disease (AD)." (PMID 27558862, 2016).